TAGLN (transgelin)
Diseases named in the same sentence as TAGLN in open-access papers (continued):
Sharing a sentence is not in itself a finding about the gene and the disease.
gastric cancer (14 papers, 2012 to 2024). A primary or metastatic malignant neoplasm involving the stomach. "QRT-PCR and Western blot indicated that TAGLN expression was upregulated in gastric carcinoma-associated fibroblasts (CAFs) that promote gastric cancer cell migration and invasion." (PMID 23510049, 2013). "Therefore, the up-regulation of transgelin in our results is in agreement with previous studies since gastric ulcer might be one of the principal risk factors of gastric cancer." (PMID 31391093, 2019). "Stromal TAGLN levels are enhanced during gastric cancer progression and related to tumor metastasis through increased matrix metalloproteinase-2 signaling." (PMID 36990991, 2023). "Our data are in line with those of a previous study in gastric cancer, in which TAGLN overexpression in stromal fibroblasts promoted tumor metastasis." (PMID 36990991, 2023). "Stromal fibroblasts in the microenvironment trigger gastric carcinoma metastases through the upregulation of TAGLN." (PMID 35178409, 2021). "It was reported that the upregulation of transgelin in stromal fibroblasts promoted gastric cancer cell migration and invasion by inducing the expression of matrix metalloproteinase-2 (MMP-2)." (PMID 25109740, 2014). "To c1arify the role of TAGLN in stromal fibroblasts during gastric cancer tumorigenesis and metastasis, we silenced the TAGLN expression in human CAFs." (PMID 23510049, 2013). "The experiment was designed to investigate the effects of stroma TAGLN, which was secreted by fibroblasts, on human gastric cancer cells." (PMID 23510049, 2013). "It is reported that the TAGLN protein is overexpressed in gastric cancer when protein expression spectrum of gastric cancer was analyzed using two-dimensional gel electrophoresis (2-DE)." (PMID 23510049, 2013). "We investigated the interaction between cancer cells and the tumor microenvironment to determine how the fibroblasts from human gastric carcinoma facilitate tumorigenesis through TAGLN." (PMID 23510049, 2013). "TAGLN is expressed in fibroblasts and smooth muscle, and the overexpression of TAGLN has been found in the tumor-induced reactive myofibroblastic stromal tissue in lung adenocarcinoma, as well in carcinomas of the stomach, liver, and oesophagus." (PMID 34771544, 2021). "This up‐regulation of TAGLN in CAFs is in agreement with studies demonstrating up‐regulation of this protein in the majority of PCa‐derived CAFs and in gastric carcinoma‐derived CAFs where it regulates CAF‐mediated metastasis of cancer cells through the regulation of MMP2 expression." (PMID 28510269, 2017). "TAGLN levels were elevated in human gastric cancer stroma than normal gastric stroma and associated with differentiation and lymph node metastasis of gastric cancer." (PMID 23510049, 2013). "We next investigated whether the invasion and migration ability of gastric cancer cells will be enhanced by the expression of TAGLN in fibroblasts, we carried out cell invasion and migration assay in vitro." (PMID 23510049, 2013). "Taken together, we suggest that TAGLN might be responsible for the enhancement of gastric cancer cell metastasis via stromal cells such as CAFs." (PMID 23510049, 2013). "Hence, we choosed MKN-45 cell line, because its TAGLN expression level was the lowest in seven gastric cancer cell lines (SNU-1, AGS, NCI-N87, KATOIII, MKN-45, MKN-28 and SGC-7901; data not shown)." (PMID 23510049, 2013). "In summary, our study demonstrates that CAFs may promote gastric cancer cell migration and invasion via increased MMP-2 production caused by TAGLN upregulation." (PMID 23510049, 2013). "Also, we used QRT-PCR and Western blot to evaluate the expression of TAGLN in gastric cancer tissues." (PMID 23510049, 2013). "CAFs may promote gastric cancer cell migration and invasion via upregulating TAGLN and TAGLN induced MMP-2 production." (PMID 23510049, 2013). "The internal levels of TAGLN in gastric cancer cells might interfere the experimental process." (PMID 23510049, 2013).
gastric cancer (continued). "Although STF1 and STF3 clusters exhibited upregulation of FAP, ACTA2, and TAGLN, the STF2 cluster exhibited upregulation of only CSPG4, further indicative of distinct CAF sublineages in gastric cancer." (PMID 34642171, 2022). "We mixed TAGLN siRNA CAFs, non-silenced CAFs, CPFs and NFs with MKN-45 human gastric cancer cells in a 2:1 ratio or MKN-45 alone and inoculated these cells through tail intravenous injection in immunodeficient nude mice." (PMID 23510049, 2013).
prostate carcinoma (14 papers, 2012 to 2025). A carcinoma that arises from epithelial cells of the prostate gland. "Transglutamine protein (TAGLN) is an important actin-associated protein, which has been found to be expressed at significantly reduced levels in a variety of cancers, including prostate cancer." (PMID 41181151, 2025). "TAGLN gene function has been associated with increased senescence in fibroblasts, and with increased apoptosis in glomerular epithelial cells and prostate cancer cells." (PMID 26421063, 2015). "In prostate cancer cells, Transgelin inhibits the binding of androgen receptor coactivators to androgen receptors." (PMID 34552870, 2021). "Previous studies have indicated that TAGLN is a TGFβ-inducible gene of human skeletal stem cells, prostate carcinoma cells, and prostate fibroblast cells." (PMID 31591355, 2019). "We therefore investigated the relationship between SM22/transgelin and the organization of the actin cytoskeleton, cell migration and response to stress in fibroblast and prostate cancer cell lines." (PMID 22257561, 2012). "As a tumor suppressor, TAGLN has been shown to inhibit prostate cancer cell growth." (PMID 34001947, 2021). "The down regulation of transgelin can be correlated to the prostate cancer progression, it may be used as a marker for cancer in addition to provide a target for novel cancer therapies." (PMID 27713912, 2016). "TAGLN has previously been reported to be upregulated in TGFβ1-induced stromal myofibroblasts, generating a phenotype that resembled reactive stromal cells from patients with prostate cancer." (PMID 26934553, 2016). "It has been recently demonstrated that transgelin prevents the binding of the androgen receptor co-activator to the androgen receptor resulting in the inhibition of androgen-stimulated cell growth in prostate cancer cells." (PMID 23717685, 2013). "KLK4 activated protease‐activated receptor‐1 in WPMY1 cells increasing expression of several factors (FGF1, TAGLN, LOX, IL8, VEGFA) involved in prostate cancer progression." (PMID 28510269, 2017). "TAGLN suppresses MMP9, a known element of invasion, and therefore prevents the migration of colon and prostate cancer cells." (PMID 26421063, 2015).
lung fibrosis (10 papers, 2007 to 2024). "Transgelin is associated with cellular changes in idiopathic pulmonary fibrosis (IPF) and was previously proposed to be a candidate tumor antigen." (PMID 17488504, 2007). "Previous studies have focused on the role of TAGLN in pulmonary fibrosis models as well as in the lung tissue of patients with idiopathic pulmonary fibrosis." (PMID 39375532, 2024). "The previous investigations have elucidated that transgelin takes parts in the process of lung cancer, asthma, and lung fibrosis." (PMID 39676863, 2024). "Transgelin has been identified as a direct target of TGF‐β/Smad3 signaling in alveolar epithelial type II cells in lung fibrosis." (PMID 32583562, 2020). "Another protein, TAGLN (transgelin), is a direct target of TGFβ-/Smad3-dependent epithelial cell migration in lung fibrosis." (PMID 30774578, 2019). "Moreover, pulmonary transgelin is up-regulated in pulmonary epithelial cells of mice during bleomycin-evoked lung fibrosis and lung tissues from patients with idiopathic pulmonary fibrosis." (PMID 39676863, 2024). "Like for CTGF, in pulmonary fibrosis and pulmonary hypertension an increased transgelin expression could also be described." (PMID 24828686, 2014). "Transgelin expression was specifically localized to ATII and smooth muscle cells in mouse lungs, and its expression was augmented in ATII cells in lung fibrosis." (PMID 34173041, 2021). "TAGLN is known to be involved in SMC migration via formation of podosomes and focal adhesions, as well as in lung fibrosis." (PMID 26421063, 2015). "Upon tissue injuries, transgelin is increasingly expressed in lung epithelial cells and may contribute to epithelial mesenchymal transition (EMT) in lung fibrosis." (PMID 24828686, 2014). "In addition, CC-11050 treatment significantly downregulated the expression of genes that play a key role in lung fibrosis, such as TGFB1 (16 dpi; p=0.0433), COL1A1 (16 dpi, p=0.009), TAGLN (16 dpi; p=0.0218), MYH11 (4 dpi; p=0.0042; 16 dpi; p=0.05) and SMAD2 (16 dpi; p=0.008)." (PMID 37854602, 2023).
hepatocellular carcinoma (8 papers, 2012 to 2025). A malignant tumor that arises from hepatocytes. "Transgelin has been reported to be regulated by promoter hypermethylation in breast, colorectal, malignant peripheral nerve sheath tumors and hepatocellular carcinomas." (PMID 30647847, 2018). "Besides, the promoter regions of transgelin are highly methylated in hepatocellular carcinoma." (PMID 22506042, 2012). "Tropomyosin β chain, transgelin or annexin A5, with a lower expression in CM2- treated cells compared to CM1-treated cells, are down-regulated proteins in hepatocellular carcinoma." (PMID 22506042, 2012). "The results were further validated by RT-PCR, western blot, flow cytometry or immunofluorescent staining which revealed that prominin-1, annexin A1, annexin A3, transgelin, creatine kinase B, vimentin, and EpCAM were indeed highly expressed in the CD133-positive hepatoma cells." (PMID 23170877, 2012).
lung cancer (8 papers, 2012 to 2024). A malignant neoplasm involving the lung. "Our study revealed that the high levels of stromal TAGLN is a predictive risk factor for patients with lung cancer." (PMID 36990991, 2023). "In the current study, we found that high fibroblastic TAGLN expression in human lung cancer is associated with increased cancer cell lymph node metastasis." (PMID 36990991, 2023). "Based on these findings, we surmise that stroma-derived TAGLN may be associated with human lung cancer metastasis." (PMID 36990991, 2023). "A larger sample size and more detailed clinical staging information are required to further characterize the effects of CAF-derived TAGLN on lung cancer survival." (PMID 36990991, 2023). "Here, we find that transgelin (TAGLN) protein levels increased in primary CAFs isolated from human lung cancer, compared with those in paired normal fibroblasts." (PMID 36990991, 2023). "Here we identified stromal TAGLN as a predictive factor for lymph node metastasis in human lung cancer." (PMID 36990991, 2023). "Co-localization of α-SMA, PDGFR-β, and TAGLN in three sequential sections of human lung cancer tissue microarrays revealed TAGLN localization in stromal fibroblasts." (PMID 36990991, 2023). "For example, Transgelin, an actin-binding protein downregulated in our study, is also downregulated in virally transformed human cells and in human breast, colon and lung cancers." (PMID 22355404, 2012). "In late NSCLC downregulation of contractile genes such as TAGLN were also observed, but others such as MMP1, MMP9 and SPP1 were found to be upregulated, which have functions in matrix remodelling and invasion and are linked to poor prognosis in lung cancer." (PMID 38582812, 2024). "Elevated transgelin can promote the progression of lung cancer." (PMID 39676863, 2024). "Thirdly, we did not assess the correlation between TAGLN stromal expression and potential mutations of frequent oncogenes in lung cancer." (PMID 36990991, 2023). "Targeting stromal TAGLN may present an alternative therapeutic strategy against lung cancer progression." (PMID 36990991, 2023). "Furthermore, TAGLN was mainly expressed in the stromal region in the EGFR-driven spontaneous lung cancer mice." (PMID 36990991, 2023). "In addition, future studies should complement the α-SMA/TAGLN double-staining assay in human lung cancer tissues, and subject the staining results to multivariate analysis in relation to clinical variables to further correct for tumor cellularity." (PMID 36990991, 2023). "Similarly, GPRC5A and TAGLN, two reported potential tumor suppressors in lung cancer, were also observed to be downregulated after expression of HPV16 oncogenes." (PMID 30918060, 2019). "Targeting TAGLN in CAFs may be a promising strategy for lung cancer therapy." (PMID 36990991, 2023). "IL-6 secreted by TAGLN-positive fibroblasts may promote lung cancer progression." (PMID 36990991, 2023). "Therefore, we were unable to determine whether tumor cells contribute to high TAGLN levels which in turn promotes proliferation of lung cancer cells and metastasis." (PMID 36990991, 2023). "Together, these findings suggest that TAGLN expression is essential for fibroblasts to acquire the CAF phenotype, which plays an important role in lung cancer progression." (PMID 36990991, 2023). "First, we examined TAGLN expression in human lung cancer and adjacent non-tumor tissues through IHC." (PMID 36990991, 2023). "There are only few studies on the role of TAGLN in lung cancer, especially since there are no reports on the function of TAGLN in the lung cancer stroma." (PMID 36990991, 2023). "Despite these studies, whether TAGLN promotes development of CAF phenotype in normal fibroblasts (NFs) and the mechanism by which TAGLN-positive CAFs modulate tumor, especially lung cancer, progression remain largely unclear." (PMID 36990991, 2023).
ovarian carcinoma (8 papers, 2019 to 2025). A malignant neoplasm originating from the surface ovarian epithelium. "Studies have shown that overexpression of the mechanosensitive encoding of actin cross‐linking/gelling protein TAGLN in ovarian cancer can mediate ovarian cancer stiffness regulation progression through RhoA/ROCK pathway." (PMID 39801760, 2025). "In ovarian cancer, TAGLN senses changes in environmental stiffness and mediates ovarian cancer progression by regulating the RhoA/ROCK pathway." (PMID 39781462, 2025). "In a different physiological context, TAGLN has been proposed to activate ROCK signaling in ovarian cancer and downregulate Akt signaling in smooth muscles." (PMID 39744178, 2024). "In our research, we also demonstrated that YAP could mediate Src activation regulated TAGLN expression, further revealed its role in ovarian cancer." (PMID 34538264, 2021).
aneurysm (6 papers, 2017 to 2024). Bulging or ballooning in an area of an artery secondary to arterial wall weakening. "We found that COL4A2, MYLK, VCL, and TAGLN may be related to aneurysm development." (PMID 33389819, 2021). "While the iPSC-derived SMC model represents newly-formed, immature SMCs rather than “de-differentiated” cells identified in aneurysm tissue, we identified reduced expression of the contractile marker TAGLN in MFS LM compared to NC SMCs." (PMID 33230159, 2020).
lung adenocarcinoma (6 papers, 2019 to 2023). A carcinoma that arises from the lung and is characterized by the presence of malignant glandular epithelial cells. "TAGLN was upregulated in cell lines from the human lung adenocarcinoma under hypoxic conditions that caused the migration ability of the tumor cells; moreover, a high TAGLN expression correlated with an advanced TNM stage, lymph node metastasis, and greater differentiation in lung adenocarcinoma." (PMID 31591355, 2019). "A high expression of TAGLN was correlated with advanced TNM stage of lung adenocarcinoma." (PMID 36982651, 2023). "Furthermore, overexpression of TAGLN was strictly localized to the tumor-induced reactive myofibroblastic stromal tissue compartment in lung adenocarcinoma suggesting TAGLN as a marker of active stromal remodeling in the vicinity of invasive carcinomas." (PMID 37296997, 2023). "Notably, the expression of TAGLN is significantly induced by hypoxia in lung adenocarcinoma." (PMID 32410620, 2020).
lymph node metastasis (6 papers, 2013 to 2025). "High expression of TAGLN was associated with advanced grading, lymph node metastasis, and poor prognosis, compared to low expression of TAGLN." (PMID 38514830, 2024). "Enhanced stromal TAGLN levels are considered an independent risk factor for lymph node metastasis." (PMID 36990991, 2023). "Although TAGLN is traditionally considered a tumor suppressor in various cancers, our study uncovers elevated TAGLN expression closely associated with adverse clinical parameters, including poor survival, advanced grading, and lymph node metastasis in HNSCC patients." (PMID 38514830, 2024). "Surrogate endpoints included recurrence, lymph node metastasis, and epithelial–mesenchymal transition, as demonstrated for miR-1307-5p and transgelin mRNA/miR-145-5p." (PMID 41149126, 2025). "In this study, we showed a correlation between cancer cell lymph node metastasis and high stromal TAGLN levels using TMAs." (PMID 36990991, 2023). "Further data analysis revealed that increased stromal TAGLN expression was correlated with positive lymph node metastasis (p = 0.0001), higher Tumor Node Metastasis (TNM) stage (p = 0.0003), and higher histopathological grade (p = 0.0383)." (PMID 36990991, 2023). "Moreover, TAGLN levels was correlated with lymph node metastasis (P = 0.029)." (PMID 23510049, 2013). "We found that the TAGLN was significantly increased in lymph node metastasis group than lymph node negative group." (PMID 23510049, 2013).
pulmonary arterial hypertension (6 papers, 2018 to 2025). Pulmonary arterial hypertension (PAH) is a group of diseases characterized by mean pulmonary artery pressure >20 mmHg and elevated pulmonary arterial resistance leading to right heart failure. "CNN1 and TAGLN with ACTA2 were implicated in Smooth Muscle Cell Dysfunction in Pulmonary Hypertension (q = 2.622x10-3)." (PMID 39480826, 2024). "Transgelin protein may be an indicator of the development of pulmonary arterial hypertension related to congenital heart disease and a potential therapeutic target for the treatment of pulmonary arterial hypertension related to congenital heart disease." (PMID 40727109, 2025). "In congenital heart disease pulmonary arterial hypertension (CHD-PAH), transgelin is significantly upregulated in the lung tissue." (PMID 34659373, 2021). "Studies on patients with pulmonary arterial hypertension (PAH) in congenital heart disease (CHD) showed that TAGLN overexpression may promote the proliferation, migration, and cytoskeleton strengthening of pulmonary arterial smooth muscle cells (PASMCs)." (PMID 36034815, 2022). "The avoidance of pulmonary hypertension is due to the increased expression of GNG2 and CA2 and the decreased expression of TAGLN and MPO, and the increased vascular permeability is due to the increased expression of GNG2 and the decreased expression of GSN." (PMID 36009723, 2022).
asthma (5 papers, 2021 to 2025). "This study confirmed the expression of peptides corresponding to ACTA2, ACTB, ACTG1, MYH11, FLNA, MYL9, and TAGLN in both control guinea pigs and the asthma model." (PMID 40980809, 2025). "In addition, the expression of transgelin is elevated in the airway smooth muscle cells of rodent asthma models." (PMID 39676863, 2024). "Based on immunohistochemistry data, the interactomes related to the expression of MYH11, MYL9, ACTG1, ACTA2, ACTB, TAGLN, and FLNA in the bronchial smooth muscle of guinea pigs in an asthma model were generated." (PMID 40980809, 2025). "MYH11, MYL9, ACTA2, and TAGLN are involved in various pathologies, including the excessive contraction observed in ASM in asthma." (PMID 40980809, 2025). "TAGLN increased (p < 0.01) and FLNA expression decreased (p < 0.05, n = 5 each group) in smooth muscle from the trachea in asthma model guinea pigs compared to controls." (PMID 40980809, 2025).